HHEX (hematopoietically expressed homeobox)
Diseases named in the same sentence as HHEX in open-access papers:
HHEX is named in the same sentence as 51 diseases in open-access papers, as found by Europe PMC text mining. Sharing a sentence is not in itself a finding about the gene and the disease. The quoted sentences say what the papers report.
type 2 diabetes (31 papers, 2007 to 2025). "The serum fasting glucose level is a basic indicator of diabetes, and several genome-wide association studies (GWAS) examining type 2 diabetes have reported that the hematopoietically expressed homeobox (HHEX) (MIM 604420) gene is a candidate causal gene." (PMID 29720110, 2018). "The hematopoietically-expressed homeobox (HHEX) gene is identified as a promising candidate for type 2 diabetes by genome-wide association studies, triggering plenty of subsequent replications; however, the results are conflicting." (PMID 23166797, 2012). "The gene encoding hematopoietically-expressed homeobox (HHEX) has been repeatedly identified as a promising candidate in susceptibility to type 2 diabetes by genome-wide association studies across ethnicities." (PMID 23166797, 2012). "The rs7932837 polymorphism in the Hematopoietically expressed homeobox (HHEX) gene was discovered through genome-wide association studies and is a promising candidate for type 2 diabetes mellitus (T2DM), which is one of the risk factors for obesity and other complications." (PMID 35197747, 2022). "Additionally, HHEX has been associated with type 2 diabetes, whereas zinc finger proteins are linked to the progression of various cancers." (PMID 35629968, 2022). "Also, the homeodomain transcription factor Hhex (hematopoietically expressed homeobox), required for delta cell differentiation, has been linked to type 2 diabetes and its deficiency released the paracrine inhibition of beta cell insulin secretion." (PMID 26236746, 2015). "Therefore, both IDE and HHEX genes are strong candidates as susceptibility genes modulating the pathogenesis of type 2 diabetes." (PMID 22506066, 2012). "Therefore, HHEX was suggested as the most likely causal candidate gene at 10q23.33 for type 2 diabetes." (PMID 22506066, 2012). "Genome-wide association studies have identified variants of HHEX associated with type 2 diabetes, and our work suggests that genetic alterations or variants of expression could be associated with the sensitivity of the adrenal gland to stress response and androgen signaling." (PMID 40321776, 2025). "HHEX is a susceptibility gene in T2DM (type 2 diabetes mellitus), and diabetes is known as a risk factor for various cancers, including CRC41." (PMID 36008411, 2022). "Both TCF7L2 variants (rs7903146 and rs12255372), HHEX rs1111875, and HNF1A rs7957197 were associated with increased risk of type 2 diabetes." (PMID 27551309, 2016). "We have previously confirmed the associations of genetic variants in HHEX, CDKAL1, VEGFA and FTO with type 2 diabetes in Han Chinese." (PMID 25587982, 2015). "Genome-wide association studies (GWAS) in populations of European ancestry have mapped a type 2 diabetes susceptibility region to chromosome 10q23.33 containing IDE, KIF11 and HHEX genes (IDE-KIF11-HHEX), which has also been replicated in Chinese populations." (PMID 22506066, 2012). "We have previously shown that type 2 diabetes risk variants in CDKAL1 and HHEX were associated with decreased beta-cell glucose sensitivity in nondiabetic individuals; however, these associations have not been tested in a larger cohort that includes subjects with abnormal glucose tolerance." (PMID 32944759, 2021). "Additionally, HHEX expression is upregulated in dermal LECs from type 2 diabetes patients, suggesting a potential lymphatic role for HHEX in pathological conditions." (PMID 30006544, 2018). "A majority of genes associated with type 2 diabetes from this meta-analysis (ADCY5, CDKAL1, CDKN2A/B, HHEX, IGF2BP2, SLC30A8, TCF7L2 and KCNQ1) are involved in pancreatic beta cell function, while two are implicated in insulin sensitivity (PPARG) and adiposity (FTO)." (PMID 25145545, 2014). "Most of the genes associated with type 2 diabetes (TCF7L2, SLC30A8, HHEX, CDKAL1, CDKN2A/B and IGF2BP2) might be implicated in beta cell function." (PMID 20161779, 2010).
type 2 diabetes (continued). "However, in 2007, several reproducible genome-wide association studies (GWASs) confirmed these well-established susceptibility genes and identified a number of new loci (SLC30A8, HHEX, CDKN2A/B, IGF2BP2, GCKR, FTO, and CDKAL1) at which common variants influence risk of type 2 diabetes in Europeans." (PMID 20161779, 2010). "Recently, several genome-wide and candidate gene association studies have identified many novel genetic loci for type 2 diabetes (T2D); among these genes, CDKAL1, IGF2BP2, SLC30A8, CDKN2A/B, HHEX, FTO, TCF2, KCNQ1, and WFS1 are the most important." (PMID 20509872, 2010). "Very recently, genetic variations within four novel genetic loci (SLC30A8, HHEX, EXT2, and LOC387761) were reported to be more frequent in subjects with type 2 diabetes than in healthy controls." (PMID 17786204, 2007).
diabetes (17 papers, 2010 to 2024). "Studies have demonstrated that several genes linked to T2DM risk are also related to GDM, and polymorphisms in HHEX, IGF2BP2, and FTO have been linked to decreased β-cell function and diabetes risk." (PMID 39659616, 2024). "WFS1 also interacts with the insulin release-related proteins (HHEX and CDKAL1), which are strongly associated with genetic risk variants for diabetes." (PMID 37185285, 2023). "Dietary habits influence the association of six genes (C2CD4B, CDKN2B, GIPR, HHEX, SLC2A2, and SLC30A8) forming the third cluster with diabetes, adipogenesis, and cardiovascular risk." (PMID 36982283, 2023). "As diabetes is a condition linked to increased cardiovascular risk, it was unsurprising that our work revealed gene interaction between KLFs, particularly KLF-14, and genes associated with diabetic risk factors, such as CAMK1D, HHEX, JAZF1, and TCF7L2." (PMID 38672763, 2024). "In the “Maturity onset diabetes of the young” pathway, the upregulation of HHEX and downregulation of HES1 could increase the expression of NEUROG3 and outcomes such as the Insulin signaling pathway." (PMID 36835058, 2023). "We aimed to characterise the possible longitudinal associations of common diabetes-susceptibility variants in the KCNJ11, PPARG, TCF7L2, IGF2BP2, CDKAL1, SLC30A8 and HHEX gene loci, with fasting glucose level; and of an obesity-associated variant in the FTO gene, with body mass index (BMI)." (PMID 20929593, 2010). "In addition, genes in the mature onset diabetes in young people (hsa04950) pathway (such as HES1, GCK, FOXA3, MAFA, HNF4A, HHEX, and PDX1) were increased in stages II to IV; these genes are related to insulin secretion and the maturation of pancreatic β-cells." (PMID 33897780, 2021). "Furthermore, several genes involved in the endocrine specification and diabetes development were significantly downregulated, such as HES1, INSM1, HNF1A, NEUROD1, NGN3, NKX2.2, GIPR, MNX1, PROX1, TCF7L2, and HHEX." (PMID 33473118, 2021). "A more recent study on genome-wide DNA methylation of pancreatic islets showed that DNA methylation patterns of T2D candidate genes, including the TCF7L2, FTO and HHEX, were altered in human islets from patients with T2D compared to controls without diabetes." (PMID 28067832, 2017).
breast carcinoma (8 papers, 2006 to 2023). "Thus, HHEX gene expression appears to be downregulated in breast cancer cells and this is associated with a poor outcome." (PMID 28604763, 2017). "HHEX expression was also confirmed to be lower in human breast cancer compared to pre-cancerous tissue, potentially contributing to the worse clinical outcomes observed in breast cancer patients bearing low levels of HHEX expression." (PMID 37398663, 2023). "Previously, HHEX was reported to act as a tumor suppressor in breast cancer and prostate cancer." (PMID 36008411, 2022). "PRH/HHEX (proline-rich homeodomain/haematopoietically expressed homeobox) is a transcription factor that displays both tumour suppressor and oncogenic activity in different disease contexts; however, the role of PRH in breast cancer is poorly understood." (PMID 28604763, 2017).
Obesity (6 papers, 2009 to 2023). Accumulation of substantial excess body fat. "We genotyped nine SNPs reported in GWAS of obesity and/or T2D, including SNPs in HHEX, KCNJ11, SLC30A8, FTO, CDKN2, CDKAL1, TCF2, and the rs9300039 SNP in an intergenic region, in 561 colon cancer cases and 721 population controls." (PMID 27990199, 2009). "The exact structure of the HHEX protein, as well as its function and relationship to obesity, are still unknown." (PMID 35197747, 2022).
thyroid dysgenesis (3 papers, 2016 to 2021). "Notably, eight mutations in four genes (FOXE1, NKX2-1, PAX8 and HHEX) that lead to thyroid dysgenesis were identified in eight probands." (PMID 29650690, 2018). "The possible causes of thyroid dysgenesis include the impact of maternal antithyroid immunoglobulins, genetic mutations, and genes of transcription factors, such as TITF1/NKX2–1, PAX8, FOXE1, and HHEX." (PMID 34713843, 2021).
acute myeloid leukemia (2 papers, 2022). Acute myeloid leukemia (AML) is a group of neoplasms arising from precursor cells committed to the myeloid cell-line differentiation. "For example, HHEX functions as an oncogene or a tumor suppressor in different subtypes of acute myeloid leukemia (AML) and CML15." (PMID 36008411, 2022).
colitis (2 papers, 2022 to 2026). Inflammation of the colon. "We recently reported that the transcription factor hematopoietically expressed homeobox (HHEX) promotes colitis-associated colorectal cancer, but the potential role of HHEX in intestinal inflammation remains uncharacterized." (PMID 41842946, 2026). "Here, we found that HHEX is upregulated in inflamed colons in a colitis mouse model and in clinical IBD samples." (PMID 41842946, 2026).
gestational diabetes mellitus (2 papers, 2018 to 2020). "Another recent study suggested the association of the HHEX gene rs5015480 polymorphism with risk of gestational diabetes mellitus in women." (PMID 29720110, 2018).
leukemia (2 papers, 2022). A malignant (clonal) hematologic disorder, involving hematopoietic stem cells and characterized by the presence of primitive or atypical myeloid or lymphoid cells in the bone marrow and the blood. "The ability of CK2 to phosphorylate the homeodomain of HHEX and therefore inhibit its nuclear localization and DNA binding, eventually inactivating the transcriptional repressor function of HHEX on the VEGF signaling pathway, was first found in K562 leukemia cells." (PMID 36008411, 2022).
T-cell lymphoma (2 papers, 2019 to 2020). "The most widespread overexpressed NKL homeobox genes in T-cell lymphomas were HHEX, HLX, MSX1 and NKX2-3, all members of the NKL-code." (PMID 31143370, 2019). "Moreover, analysis of expression profiling data from selected ALCL (GSE19069) and peripheral T-cell lymphoma patients (GSE6338) showed correlated activities of HHEX, CASP8, FOXO3 and BHLHE40, supporting this regulatory connection." (PMID 32922661, 2020).
acute lymphoblastic leukaemia (1 paper, 2016). "Recent work has shown that elevated Prh/HHEX expression occurs in Early T cell progenitor acute lymphoblastic leukaemia (ETP-ALL) and that this gene is a direct target of the LMO2 oncoprotein." (PMID 26877867, 2016).
Autoimmunity (1 paper, 2022). The occurrence of an immune reaction against the organism's own cells or tissues. "In fact, many genetic variants implicated in autoimmunity exhibit their greatest regulatory potential in GC-associated cellular populations, including BCL6 and transcription factors regulating B cell differentiation, such as POU domain class 2 homeobox associating factor 1 (POU2AF1) and HHEX." (PMID 35887298, 2022).
bladder tumors (1 paper, 2023). "Together, the existing literature and our data led us to propose a model in which the expression level of HHEX might show differential effects depending on the interplay with other repressors, such as HES1, and the status and the grade of bladder tumors." (PMID 36980177, 2023).
cervical squamous cell carcinoma (1 paper, 2023). A squamous cell carcinoma arising from the cervical epithelium. "The methylation status of Hhex was also shown to be relevant in cervical squamous cell carcinoma (CSCC), where hypomethylated HHEX was also observed as a positive prognostic indicator in patients." (PMID 37398663, 2023).
cholangiocarcinoma (1 paper, 2022). A carcinoma that arises from the intrahepatic biliary tree (intrahepatic cholangiocarcinoma) or from the junction, or adjacent to the junction, of the right and left hepatic ducts (hilar cholangiocarcinoma). "Recently, HHEX has been shown to be an oncogenic driver in cholangiocarcinoma through transcriptionally activating the Wnt and NOTCH pathways." (PMID 36008411, 2022).
hepatocellular carcinoma (1 paper, 2024). A malignant tumor that arises from hepatocytes. "Accumulating evidence indicated that HHEX participated in the initiation and development of several cancers, but the potential roles and mechanisms of HHEX in hepatocellular carcinoma (HCC) were largely unclear." (PMID 38844969, 2024).
Insulin resistance (1 paper, 2022). Increased resistance towards insulin, that is, diminished effectiveness of insulin in reducing blood glucose levels. "The genetic variants related to T2DM in Caucasians are mainly related to insulin resistance, but those in Asians, including Chinese, Japanese, and Koreans, are involved in insulin secretion (GLP1R, PAX4, HNF4A, SLC30A8, HHEX, CDKAL1, CDKN2A/B, and GCKR)." (PMID 35956399, 2022).
liver cancer (1 paper, 2022). An epithelial or non-epithelial malignant neoplasm that arises from the liver. "In contrast to the downregulation and aberrant nuclear localization of HHEX identified in breast, prostate, and liver cancers, we found that HHEX is upregulated during the progression of CRC and that an elevated expression level of HHEX is correlated with poor prognosis in CRC patients." (PMID 36008411, 2022).
multiple sclerosis (1 paper, 2022). A progressive autoimmune disorder affecting the central nervous system resulting in demyelination. "One of the multiple sclerosis (MS) risk polymorphisms, rs7923837, maps near the HHEX (hematopoietically-expressed homeobox) gene." (PMID 35887298, 2022).
T-cell leukemia (1 paper, 2016). A malignant disease of the T-lymphocytes in the bone marrow, thymus, and/or blood. "Furthermore, HHEX expression is downmodulated also in the T-cell lineage and this downregulation is physiologically critical since HHEX overexpression in these cells determines the development of T-cell leukemia in mice." (PMID 27052408, 2016).
teratocarcinoma (1 paper, 2022). A germ cell tumor characterized by the presence of an embryonal carcinoma component and a teratoma component. "Although HHEX functions as a transcriptional coactivator for SRF in fibroblasts and inhibits Jun-mediated gene activation in teratocarcinoma, it is likely that HHEX coordinates with SRF and AP1 to positively regulate YAP/TEAD activity in CRC." (PMID 36008411, 2022).
tumor (8 papers, 2006 to 2022). "HHEX was identified as a gene of interest because it was downregulated in tumor tissues and was associated with prolonged OS." (PMID 33827590, 2021). "Thus, HHEX activity is associated with apoptosis and differentiation, indicating tumor suppressor activity in ALCL." (PMID 32922661, 2020). "Thus, HHEX is the second identified NKL homeobox gene after MSX1 representing a tumor suppressor as well as an oncogene." (PMID 32922661, 2020). "Next, we confirmed the increased expression of HHEX in 6 paired primary and metastatic CRC tissues at both the mRNA and protein levels; these results indicated a potential role of HHEX in tumor metastasis in CRC." (PMID 36008411, 2022). "Our study of NKL homeobox genes HHEX and HLX in ALCL documents their impact in (deregulated) cell differentiation: HLX as oncogene and HHEX as tumor suppressor gene." (PMID 32922661, 2020).
cancer (7 papers, 2006 to 2025). A tumor composed of atypical neoplastic, often pleomorphic cells that invade other tissues. "These seemingly contradictory roles of HHEX in the regulation of gene expression may be mediated through multiple mechanisms, such as posttranslational modification statuses of HHEX, diverse binding partners of HHEX, and different epigenetic states of target genes in various cancers." (PMID 36008411, 2022).
HHEX also shares sentences with these, for which no sentence is quoted: anaplastic large cell lymphoma (2 papers); breast tumour (2); colorectal cancer (2); malignant thyroid tumors (2); Papillary thyroid carcinoma (2); thyroid cancer (2); abnormal glucose tolerance (1); carcinoid (1); colon cancer (1); dyslipidemia (1); Ewing sarcoma (1); Hodgkins lymphoma (1); infection (1); kidney (1); lymph node metastasis (1); maturity-onset diabetes of the young (1); multiple myeloma (1); neuroblastoma (1); neuroendocrine carcinoma (1); Pan (1); pancreatic ductal adenocarcinoma (1); prediabetes (1); prostate carcinoma (1); Stroke (1); synucleinopathy (1); T-lymphoblastic lymphoma (1); thyroid (1); thyroid tumours (1).